SLITRK2 (SLIT and NTRK like family member 2)
Description:
It is involved in synaptogenesis and promotes excitatory synapse differentiation. Suppresses neurite outgrowth (By similarity). Involved in the negative regulation of NTRK2.
Synonyms: CXorf2; KIAA1854; SLITL1; CXorf1; TMEM257; XLID111
Tractability: Antibody: UniProt places it where antibodies can reach, with high confidence; its Gene Ontology location is reachable by antibodies, with high confidence; UniProt predicts a signal peptide or a membrane-spanning region. PROTAC: its protein half-life has been measured.
Gene: Protein-coding gene on chromosome X (145,817,819 to 145,829,856, forward strand). Ensembl gene ENSG00000185985.
Subcellular location: Membrane; Cell membrane; Cell projection, dendrite
Pathways (Reactome):
Neuronal System: Receptor-type tyrosine-protein phosphatases
Gene Ontology:
Molecular function: protein binding
Biological process: axonogenesis; regulation of presynapse assembly; regulation of synapse organization; synaptic membrane adhesion; positive regulation of synapse assembly
Cellular component: dendrite; GABA-ergic synapse; glutamatergic synapse; plasma membrane; membrane; postsynaptic membrane
Gene-disease validity (ClinGen):
ClinGen rates the evidence that SLITRK2 causes each of these diseases.
X-linked complex neurodevelopmental disorder (X-linked): Limited. A complex neurodevelopmental disorder that is transmitted via X-linked inheritance, and is characterized by intellectual disability, autism and epilepsy.
Homologues: Orthologues: chimpanzee SLITRK2 (99% identical), macaque SLITRK2 (99% identical), dog SLITRK2 (98% identical), rabbit SLITRK2 (98% identical), pig SLITRK2 (98% identical), mouse Slitrk2 (98% identical), rat Slitrk2 (98% identical), tropical clawed frog slitrk2 (83% identical), zebrafish slitrk2 (74% identical). Paralogues in human: SLITRK5 (52% identical), SLITRK3 (44% identical), SLITRK4 (42% identical), SLITRK6 (39% identical), SLITRK1 (36% identical), SLIT3 (18% identical), SLIT2 (18% identical), SLIT1 (17% identical), TLR9 (16% identical), GP5 (14% identical), LRRN2 (14% identical), LINGO1 (14% identical), and 13 more.
Diseases named in the same sentence as SLITRK2 in open-access papers:
SLITRK2 is named in the same sentence as 19 diseases in open-access papers, as found by Europe PMC text mining. Sharing a sentence is not in itself a finding about the gene and the disease. The quoted sentences say what the papers report.
developmental delay (2 papers, 2022 to 2023). "In the current study, we identified SLITRK2 variants in NDD characterized by developmental delay and speech delay, mild to severe ID, and various neurological and behavioral comorbidities." (PMID 35840571, 2022).
Intellectual disability (2 papers, 2023 to 2024). "Mutations in SLITRK2 result in moderate to severe intellectual disability with a range of behavioral and neuropsychiatric symptoms." (PMID 39019033, 2024).
Anxiety (1 paper, 2022). Intense feelings of nervousness, tension, or panic often arise in response to interpersonal stresses. "Future studies utilizing knock-in mice expressing disease-associated SLITRK2 variants should help resolve this issue using additional behavioral paradigms that examine anxiety-like behavior." (PMID 35840571, 2022). "Moreover, most patients harboring potential disease-causing variants in SLITRK2 are anxious, whereas Nestin-Slitrk2 mice appeared to exhibit reduced anxiety-like behavior in the elevated plus-maze tests." (PMID 35840571, 2022). "However, Nestin-Slitrk2 mice exhibited reduced anxiety-like behavior, as evidenced by increased time spent in open arms (with a similar number of entries into each open arm) in the elevated plus-maze test, without a change in time spent in the light compartment in the light-dark test." (PMID 35840571, 2022).
bipolar disorder (1 paper, 2022). A disorder of the brain that causes unusual shifts in mood, energy, activity levels and the ability to carry out day-to-day tasks. "Some studies suggested SLITRK2 as a candidate gene of bipolar disorder." (PMID 35222660, 2022).
brain tumors (1 paper, 2015). "TMEM47 and SLITRK2 are linked to neuronal development and/or brain tumors." (PMID 25926557, 2015).
breast carcinoma (1 paper, 2015). "These genes likely play critical roles in cancer progression because cBioPortal analysis revealed amplification and /or mutations of TMEM47, LYPD1 and SLITRK2 in a variety of cancers including breast cancer." (PMID 25926557, 2015). "Four percent of patient-derived breast cancer xenografts in the cBioPortal show amplification of LYPD1 and mutation in SLITRK2." (PMID 25926557, 2015). "We next determined whether the expression of LYPD1, TMEM47 and/or SLITRK2 is enriched in a specific intrinsic subtype of breast cancer." (PMID 25926557, 2015).
dyslexia (1 paper, 2005). A learning disorder characterized by an impairment in processing written words. "Furthermore, a recently identified dyslexia susceptibility locus on Xq27.3 includes the SLITRK2 and SLITRK4 genes, which belong to the SLIT and NTRK-like family of genes involved in mouse neurite outgrowth and show high homology to Slit proteins." (PMID 16254601, 2005).
Dystonia (1 paper, 2022). An abnormally increased muscular tone that causes fixed abnormal postures. "Because some NDD patients reported in the current study suffer from spasticity and/or dystonia and unsteady gait, we also examined whether Nestin-Slitrk2 mice exhibit deficits in fine motor coordination." (PMID 35840571, 2022).
fragile X syndrome (1 paper, 2020). A genetic syndrome caused by mutations in the FMR1 gene which is responsible for the expression of the fragile X mental retardation 1 protein. "Genes which regulate axon growth and pathfinding as well as terminal branching of axons such as SEMA3C and SLITRK2 and SLITRK4 were found downregulated in iNeurons from patients with Fragile X syndrome, an ID disorder associated with epigenetic dysregulation." (PMID 32562237, 2020).
pancreatic cancer (1 paper, 2022). "This included elements of the Hedgehog signaling pathway (SHH, GAS1), semaphorin signaling (SEMA3A, PLXNA1, PLXNB2, PLXND1, PLXNA2, FARP1, FARP2) and also axon guidance pathways (ROBO1, SLIT1, SLIT3 and SLITRK2), all notable for their involvement in pancreatic cancer progression and metastasis." (PMID 36429078, 2022).
schizophrenia (1 paper, 2025). A major psychotic disorder characterized by abnormalities in the perception or expression of reality. "Analyses of Slitrk2 V89M knock-in mice revealed that this schizophrenia-associated substitution acts uniquely as a loss-of-function mutation in some microcircuits to impair excitatory synaptic transmission, asynchronous release, and spatial reference memory." (PMID 41411344, 2025). "This study in mice shows that each paralog acts on distinct hippocampal subfields and through different binding partners, and provides insight onto the mechanistic basis of one Slitrk2 substitution's association with schizophrenia." (PMID 41411344, 2025).
Strabismus (1 paper, 2025). A misalignment of the eyes so that the visual axes deviate from bifoveal fixation. "We noted the downregulation of SLITRK2 in cells with the strabismus-associated duplication, suggesting that a possible mechanism by which the duplication leads to strabismus is the downregulation of SLITRK2 and a resulting poor maintenance of excitatory synapses." (PMID 39858627, 2025).
neurodevelopmental disorder (4 papers, 2022 to 2025). A behavioral and cognitive disorder with onset during the developmental period that involves impaired or aberrant development of intellectual, motor, or social functions. "Missense variants in SLITRK2 cause a neurodevelopmental disorder; unfortunately, ocular phenotypes of the patients were not reported." (PMID 39858627, 2025). "In conclusion, we have reported a novel de novo variant in SLITRK2 associated with neurodevelopmental disorders with additional features including facial abnormalities." (PMID 38283150, 2023). "Herein, we report a novel nonsense variant of SLITRK2 in a boy that further confirms the role of SLITRK2 in human neurodevelopmental disorders." (PMID 38283150, 2023). "This study will aid in expanding the variant spectrum of SLITRK2-related neurodevelopmental disorder and help with the proper genetic counselling of the affected family." (PMID 38283150, 2023). "To date, a few variants have been identified in SLITRK2, which underlie neurodevelopmental disorders." (PMID 38283150, 2023). "Taken together, these data suggest that one subset of SLITRK2 variants observed in patients with neurodevelopmental disorders causes improper biochemical processing and abnormal trafficking." (PMID 35840571, 2022). "This study identifies X-linked SLITRK2 variants that underlie neurodevelopmental disorders by impairing excitatory synapses." (PMID 35840571, 2022). "In the present study, we report on rare variants (one nonsense and six missense variants) in SLITRK2 on the X chromosome identified by exome sequencing in individuals with neurodevelopmental disorders." (PMID 35840571, 2022).
brain disorder (1 paper, 2025). A disease affecting the brain or part of the brain. "The current study demonstrated that circuit-specific impairment of a particular synaptic transmission mode might underlie the manifestations of brain disorders associated with Slitrk2 dysregulation." (PMID 41411344, 2025).
SLITRK2 also shares sentences with these, for which no sentence is quoted: speech delay (2 papers); cancer (1); emphysema (1); gastric cancer (1); psychiatric disorder (1).